IL10 (interleukin 10)
Diseases named in the same sentence as IL10 in open-access papers (continued):
Sharing a sentence is not in itself a finding about the gene and the disease.
Crohn disease (continued). "Furthermore, IL-10 is such a potent regulator of overexuberant immune responses that there has been a human clinical trial of a commensal bacterial strain Lactococcus lactis expressing IL-10 to combat Crohn's disease." (PMID 24719769, 2014). "Indeed, IL-10 is very important in maintaining intestinal homeostasis as revealed by the spontaneous chronic inflammatory disease (similar to Crohn's disease) that IL-10 knockout mice develop." (PMID 24319468, 2013). "Moreover, the 3020insC NOD2 mutant protein in patients with Crohn's disease actively inhibits IL-10 production by impairing hnRNP-A1 phosphorylation and hnRNP-A1 binding to the IL-10 locus." (PMID 23675299, 2013). "Data essentially agree with a study assessing IL-10 treatment of Crohn’s disease patients." (PMID 23382730, 2013). "To determine whether IL-10-producing B cells are present in the human intestine, we analyzed publicly available single-cell RNA-sequencing (scRNA-seq) data from small intestinal tissues of both Crohn’s disease patients and healthy individuals." (PMID 41511071, 2026). "Similarly, high-dose IL-10 in Crohn’s disease patients increased IFNγ production." (PMID 39502968, 2024). "Additionally, the reduced IL-10 sensitivity induced by ER stress particularly amplified the production of TNF and IL-23, two pro-inflammatory cytokines that have strong genetic associations with Crohn’s disease and are effective therapeutic targets in IBD." (PMID 31227842, 2019). "A lack of IL-10 leads to continuous immune activation, thereby triggering chronic inflammatory bowel diseases (such as Crohn’s disease)." (PMID 39796168, 2025). "When the gingival crevicular fluid Th17 cytokine protein expressions were analyzed in Crohn’s patients, similar expression profiles of IL-1β, IL-6, IL-10, IL-12p40, IL-12p70, IFN-γ, and tumor necrosis factor (TNF)-α were observed in Crohn’s disease patients and in systemically healthy controls." (PMID 38246944, 2024). "Similarly, risk alleles for T1D, such as Interleukin 27 (IL-27), Interleukin 10 (IL-10), and interleukin-18 receptor 1 (IL18RA), have been found to prevent Crohn’s disease." (PMID 39350769, 2024). "In Crohn’s disease, levels of ENTPD1 and IL10 were higher in Th17 cells exposed to UCB and FANA-PGK1 or FANA-ALDOA than in those exposed to UCB alone; this increase was significant in the case of IL10 and trended towards significance for ENTPD1." (PMID 36131123, 2022). "Exposure to UCB alone significantly increased the frequency of CD39+ cells and that of FOXP3+ and IL-10+ cells among Th17 lymphocytes in controls but not in patients with Crohn’s disease." (PMID 36131123, 2022). "Clinical trials using recombinant human IL-10 show only modest improvement for Crohn's disease and RA, partially due to systemic rather than cite specific administration." (PMID 30515163, 2018). "The Newcastle University RA (Dex + Vit D3) and the Crohn’s disease (Dex) trials both reported decreased CD83 expression, high CD86 expression, decreased IL-12 secretion, and elevated IL-10 secretion in their tDC products suggesting a possible tDC shared phenotype." (PMID 29075262, 2017). "A marked increase in IL-10 secretion and significant reduction in IFNγ and IL-12 production was seen in PBMC exposed to this probiotic, thus it is suggested as a potential therapeutic strategy in Crohn’s disease." (PMID 23760057, 2013). "Furthermore, IL-10 decreases inflammatory cytokines and TGF-β1 in the IL-10KO model of Crohn's disease and demonstrates a promising trend in decreasing tissue fibrosis." (PMID 23690666, 2013). "In the intestine of Crohn’s disease patients, CD14+CD11+CD163low macrophages contribute to inflammation through the induction of Th17 cells and production of inflammatory cytokines; the CD14+CD11c+163high fraction is anti-inflammatory through the production of IL-10 in normal cases." (PMID 32076066, 2020).
Crohn disease (continued). "However, side effects including fever and headaches were observed and, in Crohn’s disease patients, IL-10 administration led to elevated serum levels of IFN-γ and no improvement in disease symptoms." (PMID 23755052, 2013). "However, the work presented here clearly demonstrates that TNF is not required for the development of IBD, at least in Il10−/− mice, a model with genetic, clinical, and histologic features that closely resemble human Crohn disease (CD)." (PMID 22848611, 2012). "Interestingly, the levels of IL-10 were significantly increased in the supernatants of tol-DCs of Crohn’s disease patients compared to mDCs and iDCs and did not produce pro-inflammatory cytokines like IL-12 or IL-23 (data not included)." (PMID 23300676, 2012). "However, the clinical efficacy of systemically administered IL-10 for patients with mild to moderately active Crohn's disease has not been as effective as hoped." (PMID 16259632, 2005). "Treatment with human IL-10 has been examined in clinical trials for IBD with variable results and only modest benefits in Crohn’s disease at intermediate dosages used, but of interest, not at high doses." (PMID 30249047, 2018). "Finally, trials assessing efficacy of IL-10 administration in IBD patients, either suffering from Crohn’s disease or ulcerative colitis, once more, uncovered lack of significant clinical benefit associated with this therapeutic strategy." (PMID 23382730, 2013).
multiple sclerosis (158 papers, 2007 to 2026). A progressive autoimmune disorder affecting the central nervous system resulting in demyelination. "In multiple sclerosis patients with an acute relapse, treatment with glucocorticoids was associated with increased plasma IL-10 secretion." (PMID 37744353, 2023). "The IL-10/IL-10 receptor (IL-10R) axis plays an important role in attenuating neuroinflammation in animal models of Multiple Sclerosis (MS) and increased IL-10 has been associated with a positive response to MS disease modifying therapy." (PMID 37600781, 2023). "The aim of our study was to find an association between IL-10 rs1800871, rs1800872, and rs1800896 and IL-10 serum levels in patients with multiple sclerosis in the Caucasian population." (PMID 35741685, 2022). "Surprisingly, a stimulatory role of IL-10 in antibody production has been found to be associated with the pathogenesis of multiple sclerosis." (PMID 31940754, 2020). "IL-10-deficient mice have shown to develop more severe EAE than wild-type mice, and some IL-10 promoter polymorphisms are associated with progression of multiple sclerosis." (PMID 23738007, 2013). "In support of this notion, development of multiple sclerosis in humans is associated with defective development of Tr1 cells that secrete IL-10." (PMID 22321827, 2012). "As IL-10 has been found to be associated with a less pathogenic phenotype of Th17 cells in the mouse model of multiple sclerosis, we evaluated IL-10 responses in mice that received neutralizing antibodies to IL-4 and/or IFN-γ." (PMID 19852819, 2009). "These IL-10-producing PCs were originally derived from the small intestine and migrated to the central nervous system (CNS), an important observation given the association of the microbiota with diseases such as multiple sclerosis." (PMID 31824518, 2019). "BDNF often promotes IL-10 release, as demonstrated in multiple sclerosis studies, indicating a protective feedback mechanism." (PMID 41511349, 2025). "IL-10+ CD4+ T cells co-expressing IFN-γ or IL-17A have also been described in the affected tissues of animal models of multiple sclerosis and uveitis." (PMID 40433375, 2025). "Significant improvement in IL-10 levels was noted after vitamin D supplementation in inflammatory conditions with multiple sclerosis and congestive heart failure, and this improvement also helped to bring immune balance in controlling inflammation." (PMID 40630332, 2025). "Another study also showed that these cells expressed IL-10 transcripts and co-localized with inflammatory lesions in the brains of patients with multiple sclerosis." (PMID 41283510, 2025). "Alterations in IL-10 producing Tr1 cells were shown to regulate multiple sclerosis, type 1 diabetes, and long-term allograft survival." (PMID 38250904, 2024). "Most of the resulting pathways involved aspects of inflammation: cytokine pathways (“IL-4 signaling”, “IL-10 signaling” and “IL-12 signaling”), “Multiple Sclerosis Signaling Pathway”, “Pathogen Induced Cytokine Storm Signaling Pathway” and “Complement system”." (PMID 38321224, 2024). "IL10 plays a crucial role in the pathogenesis of multiple sclerosis (MS) and other neurological illnesses." (PMID 37808700, 2024). "Results obtained in a mouse model of human multiple sclerosis suggested that inducing local expression of IL-10 in the site of inflammation has the potential to prevent autoimmune inflammatory process in the central nervous system." (PMID 37359549, 2023). "Increased levels of TNFα, IL-6 and IL-10 were evident in the blood of an LPS-treated animal model of multiple sclerosis." (PMID 37999377, 2023). "The analysis of top canonical pathways identified three common sets of shared genes, namely, pathogenesis of multiple sclerosis, IL-10 signaling, and Th1 and Th2 activation." (PMID 36160003, 2022).
multiple sclerosis (continued). "The strength of this study was that, for the first time, we analyzed IL-10 rs1800871, rs1800872, and rs1800896 and IL-10 serum levels in patients with multiple sclerosis in the Baltic population and compared them with healthy controls without other diseases." (PMID 35741685, 2022). "Previous studies have reported reduction of the Parabacteroides in multiple sclerosis patients where its exerts a protective role by stimulating anti-inflammatory IL-10–expressing human CD4+CD25+ T cells." (PMID 33546364, 2021). "DHF upregulated IL-10, similar to our previous findings in a murine model for multiple sclerosis, a neurodegenerative disease." (PMID 34531413, 2021). "Unbiased blockade of both BR3 and TACI signal pathways will only augment inflammation due to decreased IL-10 secretion, as observed in multiple sclerosis (MS) patients." (PMID 33926416, 2021). "Beneficial anti-inflammatory effects of IL-10 have been shown in animal models of neurodegenerative diseases, such as Alzheimer’s disease, PD, and multiple sclerosis." (PMID 31940754, 2020). "A recent study investigating multiple sclerosis (MS) showed that APRIL mediated an anti-inflammatory response in astrocytes by producing IL-10 to suppress antigen-specific T-cell proliferation and pathogenic cytokine secretion." (PMID 32850873, 2020). "It has also been reported that B cells from patients with multiple sclerosis secreted markedly lower levels of IL-10, as compared with healthy donors, suggesting the possible IL-10 secretion function of B cells in humans." (PMID 33293897, 2020). "The CD46-costimulation pathway in Tr1 cells is impaired in multiple sclerosis, leading to decrease in IL-10 production." (PMID 33271810, 2020). "Investigate the effects of photobiomodulation (PBM) on the expression of IL-10 and nitrites in individuals with Relapsing-Remitting multiple sclerosis (MS), as these biomarkers play a fundamental role in the physiopathology of the disease." (PMID 32255785, 2020). "In a related report, increased levels of intestinal clostridia were correlated with impaired differentiation of IL-10-secreting regulatory T lymphocytes in vitro, an effect which contributed to an inhibition of immunoregulatory functions in multiple sclerosis." (PMID 31616319, 2019). "A recent study elegantly demonstrated the role of IL-10 producing PCs in the suppression of neuroinflammation in a mouse model of autoimmune encephalomyelitis (EAE) which recapitulates some features of multiple sclerosis (MS) in humans." (PMID 31824518, 2019). "Also, the possibility of inherent reduced capacity of DC and other immune cells of multiple sclerosis patients to produce IL-10 warrants additional studies as it might be important for understanding the predisposition of humans toward the development of multiple sclerosis." (PMID 30792716, 2019). "For a subset of n = 17 untreated multiple sclerosis patients, IL-10 levels were measured from samples at two different time points, with an average interval of 3 years." (PMID 29361022, 2018). "In multiple sclerosis (MS), melatonin blocks Th17 differentiation and boosts the generation of IL-10-secreting Treg cells by an MT1-dependent mechanism." (PMID 30349079, 2018). "The multiple sclerosis risk allele rs4810485*T, associated with lower CD40 surface expression levels in the flow cytometry data, corresponded to lower IL-10 levels." (PMID 29361022, 2018). "Further evidence of a role for pDCs and IFN-α in the expansion of CD24+CD38hi Breg cells is provided by data reporting an enrichment of IL-10+CD24hiCD38hi B cells in multiple sclerosis (MS) patients responding to IFN-β therapy." (PMID 26968426, 2016). "The key role of IL-10 released by B cells has been also proven in multiple sclerosis (MS) patients, who have B cells with impaired IL-10 production under CD40 stimulation." (PMID 27956762, 2016). "Interferon-β-treated multiple sclerosis patients had increased IL10 and IL27 gene expression levels in monocytes in vivo." (PMID 25738751, 2015).
multiple sclerosis (continued). "Specifically, RSV effect on tolerance is likely to be in the induction of Foxp3+ T cells and IL-10 expression, which are critical to development of T cells that are protective against autoimmune diseases, such as multiple sclerosis." (PMID 26441683, 2015). "We thus next investigated this possibility in a small cohort of samples from healthy controls or individuals with either multiple sclerosis (MS) or Spondylarthritis (SpA) using M0 (unstimulated), M1 (LPS/IFNγ) or M2 (IL-4/IL-10/TGF-β) polarization protocols." (PMID 24521472, 2014). "In this study, we used NSPCs overexpressing IL-10, an immunomodulatory cytokine, in an animal model for CNS inflammation and multiple sclerosis (MS)." (PMID 24053338, 2013). "Secretion of IL-10 upon CD46 costimulation is largely impaired in T cells from patients with multiple sclerosis (MS)." (PMID 23144765, 2012). "Valerio and co-workers have shown an increased IL-10 production after a plant sterol enriched diet in a multiple sclerosis (MS) model in mice, leading to improved clinical manifestations of the disease." (PMID 23091602, 2012). "Similarly to our results, calcitriol was able to restore the IL-10/IFN-γ ratio in patients with multiple sclerosis and has been shown to have a similar effect in other autoimmune or infectious diseases." (PMID 39403120, 2024). "IL-10 producing plasmablasts/plasma cells were found to be critical for suppressing excessive inflammation in an experimental autoimmune encephalomyelitis mouse model (a mouse model of multiple sclerosis) as well as in mice infected with Trypanosoma brucei." (PMID 38487540, 2024). "However, in multiple sclerosis (MS), it has been demonstrated that 5-HT acts on T cells to produce less proinflammatory cytokines and more of IL-10." (PMID 38322704, 2023). "Therefore, the aim of our study was to investigate IL-10 rs1800871, rs1800872, and rs1800896 and IL-10 serum levels in patients with multiple sclerosis in Lithuania." (PMID 35741685, 2022). "IL-10, secreted by Treg, was increased after plasma exchange in multiple autoimmune diseases, such as myasthenia gravis, thrombotic thrombocytopenic purpura, and multiple sclerosis." (PMID 35514988, 2022). "Using immunomodulation targets, IL-10 production has been considered as a therapeutic potentiation in several neurodegenerative diseases, including Alzheimer’s disease, Parkinson’s disease, and multiple sclerosis." (PMID 35010945, 2021). "Matrine (MAT), a quinolizidine alkaloid component derived from the root of Sophora flavescens, suppresses experimental autoimmune encephalomyelitis (EAE), the animal model of multiple sclerosis (MS), by inducing the production of immunomodulatory molecules, e.g., IL-10." (PMID 33101289, 2020). "Indeed, reduction in the proportion of IL-10-producing PBMC in multiple sclerosis patients, as well as of IL-10 mRNA expression in these cells were previously reported." (PMID 30792716, 2019). "Interestingly, the levels of IL-10-producing CD8 cells have been reported as significantly reduced in the exacerbation phase of multiple sclerosis but increased during remission, suggesting a favorable effect on patient recovery." (PMID 31711508, 2019). "Our data in humans, however, suggest that CD40 blockade may be counter-productive in multiple sclerosis as it may inhibit beneficial mechanisms such as IL-10 producing immunomodulatory B cells." (PMID 29361022, 2018). "In the animal model for multiple sclerosis, EAE, the transfer of regulatory IL-10 producing B cells (B10) into Cd19−/− B cell deficient mice reduces EAE severity and reduces autoantigen-specific CD4+ T cell proliferation and pro-inflammatory cytokine production." (PMID 29361022, 2018). "Results showed that: 1) the expression of IL-10 mRNA was increased in PBMCs of HC alone compared to patients with a diagnosis of PP, SP, RR and BE multiple sclerosis; and 2) TNFα mRNA was augmented only in PBMC of PPMS patients compared to SPMS, RRMS, BEMS and HC." (PMID 27412504, 2016).